EFNA3 (ephrin A3)
Diseases named in the same sentence as EFNA3 in open-access papers (continued):
Sharing a sentence is not in itself a finding about the gene and the disease.
cancer (24 papers, 2013 to 2026). A tumor composed of atypical neoplastic, often pleomorphic cells that invade other tissues. "It is increasingly evidenced that EFNA3 acts as a receptor tyrosine kinase ligand, and its expression level has been proved to be aberrant in kinds of cancers." (PMID 38009813, 2024). "But in recent years, there has been many researches about EFNA3, and its role is diverse in cancers." (PMID 38630320, 2024). "The expression of EFNA3 was elevated in pan-cancer, and the differential expression heat map of different cancers showed that it was elevated in many tumors, but significantly down-regulated in GBM." (PMID 35309935, 2022). "The results showed that EFNA1 and EFNA4 had the highest expression in pan-cancer, followed by EFNA3 and EFNA5 with high expression, and EFNA2 with low expression." (PMID 35309935, 2022). "The online data results of our study show that the expression of EFNA3 in many types of cancers differs from that in normal tissues." (PMID 35126464, 2021). "Here, we studied the expression of EFNA3 in different cancers, focusing on the high expression of EFNA3 in GC and its relationship to poor prognosis." (PMID 35126464, 2021). "As TIICs are independent predictors of cancer prognosis, it is very important to study the relationship between the expression of EFNA3 and the level of immune cell infiltration." (PMID 35126464, 2021). "Unexpectedly we found that, in cancer cell lines, hypoxia led to the HIF-dependent transcription of the lncRNAs encoded by the EFNA3 locus and had only a minor effect on EFNA3 mRNA levels." (PMID 26682249, 2015). "Here we show that in cancer cells, coexpressed ephrin-A3 can inhibit the ability of EphA2 and EphA3 to bind ephrins in trans and become activated, while ephrin-B2 can inhibit not only EphB4 but also EphA3." (PMID 24348920, 2013). "EFNA3 was upregulated in most cancer types, except for GBM, SKCM, and KICH." (PMID 36052169, 2022). "The coexpression of Ephrin-A3 can block the ability of EphA2 and EphA3 to link ephrins in trans and become activated, while Ephrin-B2 can deter not only EphB4 but also EphA3 in the cancer cells." (PMID 32368295, 2020). "In other studies, miR-210 has been shown to modulate mitochondrial oxygen uptake and create a pseudo-hypoxic environment, or to act as an oncomiR by repressing the Myc antagonist Max-binding protein (MNT) and as pro-angiomir by targeting ephrin-A3 in other cancers." (PMID 25129238, 2014). "We assessed the mRNA expression levels of LRRC15, EFNA3, TSPAN13, and CA12 in diverse cancer tissues and compared them to normal tissue using the TIMER2.0 database." (PMID 38611080, 2024). "Taken together, these findings suggest that LRRC15, EFNA3, TSPAN13, and CA12 can serve as potential biomarkers for improving cancer diagnosis screening and as suitable targets for therapy with reduced side effects and enhanced efficacy." (PMID 38611080, 2024). "Twelve components were included in the MAPK signalling pathway, and of these, EFNA3, STMN1, PAK1, and TNF have previously been found to regulate EMT in cancer progression." (PMID 37225681, 2023). "Based on RNA expression data, EFNA1 and EFNA5 were negatively correlated with the stem cell scores in most cancers, whereas EFNA2, EFNA3, and EFNA4 exhibited varying correlations with stem cell scores in different cancers." (PMID 35945523, 2022). "The correlation of EFNAs co-expression at transcriptome level in pan-cancer was first examined, and the results suggested a strong correlation between EFNA1, EFNA3, and EFNA4." (PMID 35945523, 2022). "A positive correlation was noted between the expression of EFNA1, EFNA3, EFNA4, EFNA5 and CNV in most cancer types; however, EFNA2 expression was only weakly correlated with CNV." (PMID 35945523, 2022). "The lncRNAs such as NEAT1, lincRNA‐ROR, EFNA3, and GAS5 are HSF1 targets, which are all involved in cancer." (PMID 32691951, 2020).
cancer (continued). "The role of EFNA3 in CRC angiogenesis remains unproven, although ephrin and Eph receptor over-expression has been reported in a variety of human cancers including CRC." (PMID 24180698, 2013). "Importantly, the overexpression of LRRC15, EFNA3, TSPAN13, and CA12 was observed in tissues at both early and advanced stages of cancer, indicating that these proteins hold promise as targets for early diagnosis." (PMID 38611080, 2024). "In the majority of cancers, EFNA1, EFNA2, EFNA3, and EFNA4 were suppressed by stromal and/or immune components, whereas EFNA5 demonstrated different trends in the stromal and immune scores across different cancers." (PMID 35945523, 2022). "We have shown that the levels of EphA3 on the cancer cell surface are not decreased by coexpression of ephrin-A3." (PMID 24348920, 2013). "Other studies that demonstrate upregulation of ephrin-A3 in NSCLC and inhibitory effects of ephrin-A3 and ephrin-B2 on transactivation of EphA2/EphA3 and EphA3/EphB4, respectively, are indicative of context-dependent aberrations of Eph/ephrin molecules in cancer cells." (PMID 29682554, 2018).
neurologic disease (2 papers, 2018 to 2023). "The initial observation of increased LACV susceptibility of Efna2−/− (m) adult mice with mixed Efna3/5 deficiency suggested that the EphrinA molecules might have a role in resistance to LACV-induced neurologic disease." (PMID 37202395, 2023). "Following inoculation of 105 PFU/mouse, approximately 50% of Efna2−/− (m) mice developed neurologic disease, regardless of their Efna3 or Efna5 genotype." (PMID 37202395, 2023).
kidney disease (1 paper, 2025). "There were 7 proteins that exclusively associated only with the kidney domain supporting their proximal role in kidney disease (e.g., A4GALT, PCK2, EFNA3, BTN3A2, IDI2, GATM, FAIM)." (PMID 41282674, 2025).
EFNA3 also shares sentences with these, for which no sentence is quoted: choroidal melanoma (2 papers); medulloblastoma (2); oral squamous cell carcinoma (2); acute myocardial infarction (1); amyotrophic lateral sclerosis (1); Arthritis (1); asthenia (1); brain disorder (1); cervical squamous cell carcinoma (1); clear cell renal carcinoma (1); colon adenocarcinoma (1); Crohn disease (1); endocervical adenocarcinoma (1); esophageal carcinoma (1); glioblastoma (1); IgA nephropathy (1); intervertebral disc degeneration (1); invasive breast carcinoma (1); ischemic disease (1); multiple sclerosis (1); pituitary tumour (1); prostate (1); renal cell carcinoma (1); rhabdomyosarcoma (1); rheumatoid arthritis (1); staphylococcus aureus infection (1); stomach adenocarcinoma (1); thyroid carcinoma (1); ulcerative colitis (1); uterine corpus endometrial carcinoma (1).
A further 1 disease shares a sentence with EFNA3 in 1 paper.